RAP2A (RAP2A, member of RAS oncogene family)
Diseases named in the same sentence as RAP2A in open-access papers (continued):
Sharing a sentence is not in itself a finding about the gene and the disease.
tumor (20 papers, 2007 to 2025). "As increasing evidence of Rap2a overexpression in tumor progression had been discovered, the mechanisms underlying the regulations attracted notable attention." (PMID 28747626, 2017). "It is important to assess whether Rap2a gene can be used as biomarkers to predict tumor metastasis and guide the choice of therapy, which is why we investigated the level of Rap2a expression in RCC patients as well as their associations with clinicopatological features." (PMID 28747626, 2017). "Only a few studies investigated RAP2A, which mainly focused on the molecular mechanisms of RAP2A in tumor migration and invasion." (PMID 38811930, 2024). "While, the role of RAP2A has been previously demonstrated in the regulation of lipopolysaccharide induced innate cell functions, detailed role of RAP2A in the modulation of tumor immunity remains to be studied in detail." (PMID 34235179, 2021). "In summary, our findings illustrated that miR-33a-5p acts a potential tumor suppressor in PDAC progression by targeting RAP2A, which provides a potential therapeutic strategy against PDAC." (PMID 34090323, 2021). "We paid attention to RAP2A which had been demonstrated to play a role of a tumor promoter for several tumors, including CRC." (PMID 34422671, 2021). "Further, DNA methylation at this region is negatively correlated to RAP2A gene expression in both tumor and normal tissues." (PMID 34235179, 2021). "So far, the role of RAP2A in human malignancies remains controversial, with some suggesting it as a tumor suppressor gene while other studies refer to it as an oncogene." (PMID 34235179, 2021). "Among all five RAPs, RAP2A expression exhibited a strong ability to differentiate tumor tissues from normal tissues." (PMID 34235179, 2021). "Our results highlighted a specific intragenic region in the RAP2A where DNA methylation was highly reduced in tumor tissues compared to normal liver tissues." (PMID 34235179, 2021). "Further, pathway analysis revealed that RAP2A expression is correlated with tumor-infiltrating immune cell composition and oncogenic molecular pathways, such as cell cycle and cellular metabolism." (PMID 34235179, 2021). "Using the TIMER tool, we determine tumor purity normalized spearman correlation of RAP2A expression with infiltration level of six different immune cells." (PMID 34235179, 2021). "The tumors were resected and processed for immunohistochemical staining; the results revealed that treatment with the LV-miR-199a-3p construct resulted in the decreased expression of RAP2a and DNMT3a in tumor tissues." (PMID 33365310, 2020). "Among all 32 putative target genes of miR-193a-5p, we identified four tumor-associated genes, including CUX1, ITSN1, OLA1, and RAP2A." (PMID 33014778, 2020). "We found that Rap2a expression was significantly increased in RCC tissues compared with tumor adjacent normal renal tissues." (PMID 28747626, 2017). "Our in vivo experiment about Rap2a provided more evidence to support the contribution of Rap2a overexpression in tumor development." (PMID 28747626, 2017). "Remarkably, several of these target genes were down-regulated following miR-Combo treatment, and have been shown to be involved in GBM progression (RAP2A), angiogenesis (SPON2), migration (CXCR4), and are associated with an increase in tumor grade (IGF2BP3, SERPINH1)." (PMID 37749143, 2023). "RAP2A shows a strong ability to distinguish tumor from normal tissue." (PMID 37470852, 2023). "Among all RAPs, RAP2A displayed most robust upregulation in tumor tissues in TCGA dataset." (PMID 34235179, 2021). "Taken together, these results suggest that miR-33a-5p exerted tumor suppressive effects on PDAC cells by targeting RAP2A, which might provide a new theoretical basis for the clinical treatment of PDAC." (PMID 34090323, 2021).
tumor (continued). "Moreover, via initiating the signaling pathway of AKT, the ability to invade, migrate, and metastasize for tumor cells was facilitated by RAP2A." (PMID 34422671, 2021). "Immunohistochemistry staining showed that the expression of RAP2a and DMNT3a was decreased in a xenograft model with miR-199a-3p overexpression, which suggests that both RAP2a and DMNT3a were targets of miR-199a-3p, and RAP2a and DMNT3a participate in the tumor suppression effect of miR-199a-3p." (PMID 33365310, 2020). "Meanwhile, we found that RAP2a was also a direct target of miR-199a-3p, which might mediate the tumor-growth-inhibiting effect of miR-199a-3p." (PMID 33365310, 2020). "Thus, we analyzed the expression of RAP2A in tumor and normal tissue samples using the BioXpress database, and found that RAP2A was overexpressed in several tumor types including BCA." (PMID 32194636, 2020). "The lungs in Rap2a group had more and larger detectable tumor nodules." (PMID 28747626, 2017). "In addition, we constructed RCC cell lines in which Rap2a expression over-expressed or down-regulated to examine the role of Rap2a on the proliferation, migration and invasion of tumor cells." (PMID 28747626, 2017). "Furthermore, a comparison of 47 paired normal and tumor tissue also revealed significantly reduced methylation levels of cg03608515 in tumor tissues., these results strongly suggest the role of DNA methylation in aberrant expression of RAP2A in HCC." (PMID 34235179, 2021). "MiR-10b overexpression accelerated PCC proliferation and tumor growth; miR-10b enhanced the stimulatory effects of EGF and TGF-β on cell migration and EMT, decreasing the expression of RAP2A, EPHB2, KLF4 and NF1." (PMID 29254283, 2017). "Additionally, RT‐qPCR analysis indicated that CHST9 was expressed at low levels in tumour samples, while HMGN4, ITGAV, RAP2A, TMCO3, and ZFYVE26 displayed high expression levels." (PMID 39428564, 2024). "Most studies about RAP2A and RAP2B focus on their functions in tumor." (PMID 34733151, 2021). "In CPTAC data also, RAP2A exhibited most robust upregulation of mRNA and protein levels in tumor tissues compared to normal tissues, while expression of RAP2C was found to be reduced in tumor tissues compared to normal tissues." (PMID 34235179, 2021). "Interestingly, RAP2A gene expression was reduced in tumor tissues and exhibited a negative correlation with DNA methylation at several sites within the RAP2A promoter regions and gene body." (PMID 34235179, 2021).
cancer (14 papers, 2011 to 2024). A tumor composed of atypical neoplastic, often pleomorphic cells that invade other tissues. "RAP2A is overexpressed in a multitude of human cancers and plays an important role in cytoskeleton rearrangement, arteriogenesis, and cell migration." (PMID 34733151, 2021). "RAP2a is significantly up-regulated in many types of tumors; the ectopic expression of RAP2a plays a key role in enhancing the migration and invasion ability of cancer cells." (PMID 33365310, 2020). "Rap2a, a member of the small GTPase superfamily, belongs to Ras superfamily, and its function in cancer progression is still poorly understood." (PMID 28747626, 2017). "Meanwhile, the downregulation of Rap2a inhibited the migratory and invasive capacities of cancer cells." (PMID 28747626, 2017). "Our results demonstrated that the upregulation of Rap2a promoted the migratory and invasive capacities of cancer cells." (PMID 28747626, 2017). "In CRC, RAP2A displayed high expression, serving as a cancer promotor." (PMID 34422671, 2021). "The depletion of RAP2a suppressed cancer invasion and migration." (PMID 33365310, 2020). "RAP2A was believed to be a crucial upstream activator of the PI3K/AKT pathway in cancer cells." (PMID 32194636, 2020). "In contrast, downregulation of Rap2a inhibits the migration and invasive ability of cancer cells." (PMID 28747626, 2017). "The ectopic expression of Rap2a enhanced the migration and invasive ability of cancer cells." (PMID 28747626, 2017). "Based on the result from cell migration and invasion, we then investigated whether Rap2a affects carcinoma cell proliferation." (PMID 28747626, 2017). "Thus, elevated Akt phosphorylation may participate in Rap2a mediated cancer cell migration and invasion." (PMID 28747626, 2017). "RAP2a belongs to the Ras-related small GTP-binding protein superfamily, which has been reported to affect tissue invasiveness and metastasis in many human cancers." (PMID 33365310, 2020). "To further confirm that RAP2a plays a central role in regulating cancer progression, we transfected siRAP2a into BCPAP cells to knock down the expression of RAP2a." (PMID 33365310, 2020). "DNA methylation of RAP2A has not been previously studied in cancer, therefore, epigenetic regulation of RAP signaling requires detailed exploration." (PMID 34235179, 2021). "A significant higher expression of Rap2a was observed in the carcinoma tissues when compared with normal human renal tissues (P = 0.000, χ2 test)." (PMID 28747626, 2017).
RAP2A also shares sentences with these, for which no sentence is quoted: infection (3 papers); osteosarcoma (3); thyroid cancer (3); anemia (2); breast carcinoma (2); Anxiety (1); atherosclerosis (1); colon cancer (1); epilepsy (1); hepatitis B (1); inflammatory bowel disease (1); iron deficiency (1); malaria (1); nasopharyngeal carcinoma (1); neurodegenerative disease (1); neurological disorders (1); ovarian carcinoma (1); pancreatic ductal adenocarcinoma (1); Papillary Thyroid Carcinoma (1); type 2 diabetes (1); viral infection (1); vivax malaria (1); X-linked Emery-Dreifuss muscular dystrophy (1).